CXCL12 (C-X-C motif chemokine ligand 12)
Diseases named in the same sentence as CXCL12 in open-access papers (continued):
Sharing a sentence is not in itself a finding about the gene and the disease.
breast carcinoma (continued). "In a mouse breast cancer model, vitamin D deficiency increases lung expression of CXCL-12; therefore, CXCR-4-positive tumor cells follow the CXCL-12 gradient." (PMID 37114140, 2023). "Among the signaling molecules involved with MSC migration to the tumor site are CXCL12/CXCR4, CCL2 in Breast cancer, and SDF-1 in colorectal, prostate, and breast cancers." (PMID 36674525, 2023). "A comprehensive interrogation of the prognostic implication of CXCL12 in breast cancer is eagerly needed." (PMID 37564657, 2023). "In breast cancer preclinical models, high expression of CXCL12 is linked with a prolonged disease-free survival (DFS) and overall survival (OS), presumably owing to decreased metastasis of breast cancer cells." (PMID 37564657, 2023). "Inhibition of C-X-C motif receptor 4 in fibroblasts, the receptor of CXCL12, resulted in decreased fibrosis, increased infiltration of cytotoxic T lymphocytes, and decreased immunosuppressive microenvironment in metastasized breast cancer models." (PMID 37686288, 2023). "An evaluation of cancer hallmark gene-sets associated with five continuous phenotypes C3, COL11A1, CXCL12, FBLN1, and S100A4 using the aspatial methods including GSEA, LCT, and RF-GSEA on a single cell breast cancer study." (PMID 36998245, 2023). "We aimed to comprehensively detect the role of CXCL12 in breast cancer, and explore novel CXCL12-related biomarkers through integrative multi-omics analyses to build a powerful prognostic model for breast cancer patients." (PMID 37564657, 2023). "Combined single-nucleus and spatial transcriptomics data was used to uncover the expression distribution of CXCL12 in breast cancer microenvironment." (PMID 37564657, 2023). "Given the prognostic implication of CXCL12 for breast cancer, we further devoted to uncovering the expression pattern of CXCL12 in the complex cellular clusters and architecture." (PMID 37564657, 2023). "First, the mechanisms of action of CXCL12 in breast cancer are necessary to be validated in vivo and in vitro." (PMID 37564657, 2023). "Here, we comprehensively interrogate the role of CXCL12 in breast cancer by integrative multi-omics analyses." (PMID 37564657, 2023). "The decreased CXCL12 expression level was related to poor prognosis in the public breast cancer dataset and our validation cohort." (PMID 37564657, 2023). "Next, we looked forward to further clarify the prognostic potential of CXCL12-realted genes in breast cancer." (PMID 37564657, 2023). "We found that high expression of CXCL12 was significantly linked with superior OS and recurrence-free survival (RFS) of breast cancers." (PMID 37564657, 2023). "directly targeted the CXCR4/CXCL12 signaling axis in metastatic breast cancer in vivo models with the FDA approved drug plerixafor." (PMID 38022679, 2023). "SHH expression is induced by NF-κB activation, which in turn promotes CXCL12 secretion in breast cancer cells and regulates the positive feedback loop in breast cancer TME." (PMID 38004606, 2023). "Similar beneficial effects of CXCL12 on clinical outcomes have been observed in patients with osteosarcoma and breast cancers." (PMID 37966614, 2023). "Our earlier study also reported that osteopontin (OPN)-activated CAF-derived CXCL12 promotes epithelial-to-mesenchymal transition (EMT) in breast cancer cells." (PMID 37065872, 2023). "The effects of CXCL12 and CXCL12-mediated signaling pathways in breast cancer are multifaceted and highly context-dependent, varying among different molecular subtypes, stages of tumor progression, and the microenvironmental context." (PMID 37564657, 2023). "Our findings identify a novel role for DPP-4 inhibition in the promotion of breast cancer survival by inducing CXCL12/CXCR4/mTOR/HIF-1α axis-dependent autophagy." (PMID 37760498, 2023). "Gene analyses revealed CXCL12 as an upregulated chemokine in breast cancers, showing a low cytotoxic T lymphocyte infiltration." (PMID 37686288, 2023).
breast carcinoma (continued). "The CXCL12, also known as stromal cell-derived factor-1 (SDF-1), rs2839693 variant is reported in many diseases including HIV-1, Pulmonary tuberculosis, breast cancer, and coronary artery disease." (PMID 37858116, 2023). "Spatially, we mapped CXCL12 and CAFs in the breast cancer tissue, and found overlapped regions in the spatial capture locations." (PMID 37564657, 2023). "A recent study reported that CXCL12 paracrine signaling induced liver metastasis by silencing NK cells in activated HSCs in a liver metastasis model of subcutaneous breast cancer." (PMID 37189708, 2023). "Previous studies have shown that CXCL12 is related to various cancers, including pancreatic cancer, colorectal cancer, breast cancer, and cervical cancer." (PMID 37248251, 2023). "Crucial chemoattractant molecules in breast cancer, CXCL12 and EGF, drive the activation of ERK and Akt." (PMID 36829763, 2023). "Next, we aimed to elucidate the prognostic potential of CXCL12 expression in breast cancer, we first explored the Molecular Taxonomy of Breast Cancer International Consortium (METABRIC) cohort, which was the largest breast cancer cohort so far." (PMID 37564657, 2023). "Accordingly, neutralizing the interactions of CXCL12/CXCR4 impaired metastasis of breast cancer cells to regional lymph nodes and lung." (PMID 37490147, 2023). "CXCL12 is expressed in a variety of tumors including ovarian cancer, breast cancer, glioblastoma and pancreatic cancer." (PMID 38022679, 2023). "Our validation analysis showed that higher CXCL12 expression level correlated to superior disease-free survival (DFS) in breast cancer." (PMID 37564657, 2023). "CXCL12 derived from CAFs can not only regulate the TME by targeting endothelial cells to promote breast cancer metastasis but also increase the permeability of the endothelial cell layer in a specific way." (PMID 37978384, 2023). "We depicted the CXCL12 expression pattern in the histological sections to reveal the spatial location of CXCL12-expressing cells in breast cancer tissues." (PMID 37564657, 2023). "Chemokine (C-X-C motif) receptor type 4 (CXCR4) and its ligand, chemokine (C-X-C motif) ligand type 12 (CXCL12), are relatively highly expressed in invasive breast cancer cells, homing them to distant lymph nodes, the lungs, and the liver." (PMID 36612320, 2023). "Bone marrow endothelial cells express CXCL12 and mediate adhesion and recruitment of breast cancer cells that express CXCR4." (PMID 38041134, 2023). "Among diverse PAM50 molecular subtypes, CXCL12 was strikingly higher in the normal-like subtype, which is only a small subset of breast cancers." (PMID 37564657, 2023). "In conclusion, we show here that DPP-4 inhibition accelerates breast cancer cell survival by inducing autophagy through CXCL12/CXCR4-mediated mTOR/HIF-1α activation; metformin abrogates such alterations induced by DPP-4 suppression." (PMID 37760498, 2023). "The pentacyclic triterpene polyformic acid (PA), obtained from Euscaphis japonica, inhibits the transcription and expression of the CXCR4 protein in breast cancer cells and suppresses CXCL12-induced cell invasion." (PMID 35893797, 2022). "Intriguingly, CXCL12 has also been shown to operate in an autocrine positive feedback loop to maintain an oncogenic CAF phenotype in breast cancer, where CAF-derived CXCL12 was also found to regulate cancer stem cells through activation of the NOTCH pathway." (PMID 36671452, 2022). "Using the OHD4–12, we show that the CXCL4–CXCL12 chemokine heterodimer inhibits the CXCL12-driven migration of triple-negative MDA-MB-231 breast cancer cells." (PMID 36229490, 2022). "In turn, these macrophages foster tumor growth, angiogenesis and extravasation of breast cancer cells in a CXCL12-dependent manner in vitro." (PMID 35309358, 2022).
breast carcinoma (continued). "In brain metastases from breast cancer, several immunohistochemistry-based studies have shown a strong expression of granulocyte–macrophage colony-stimulating factor (GM-CSF), C-X-C motif chemokine ligand 12 (CXCL12) and its receptor 4 (CXCR4), and CX3CL1." (PMID 36411434, 2022). "Frozen sections of surgically resected MSS PDA, MSS CRC, and breast cancer were stained with fluorochrome-conjugated antibodies to CXCL12 and keratin-19 KRT19." (PMID 35046049, 2022). "In particular the CXCR4/CXCL12 axes has been reported to control breast cancer metastasis and the involvement of CAFs." (PMID 36588678, 2022). "To determine the impact of soluble factors on breast cancer cell motility, we added either CXCL12 or epidermal growth factor (EGF), or a combination of both, to our cell cultures just prior to time-lapse video recording." (PMID 35158871, 2022). "CXCL1, CXCL2, CXCL8, and CXCL12 were observed to diminish tumor response to chemotherapy, especially in breast cancers." (PMID 36612163, 2022). "CXCR4 plays a role in the growth and metastasis of breast cancer via its ligand CXCL12/SDF-1, which activates mTOR to promote the epithelial–mesenchymal transition (EMT), and is therefore important in metastasis." (PMID 35754051, 2022). "The metastasis of breast cancer cells to lymph nodes, lungs, liver, and bone marrow is inhibited by neutralizing the interaction of cognate ligand CXCL12 (SDF-1) with its overexpressed chemokine receptor CXCR4." (PMID 36559325, 2022). "More importantly, CAFs are prone to facilitate cells migration and cancer distant metastasis in breast cancer via secretion of CXCL12." (PMID 35831824, 2022). "We have investigated in cell models representative of the major subtypes of breast cancer (BC) the interplay between the chemokine CXCL12/CXCR4/ACKR3 and EGF receptor (EGFR) family signaling cascades." (PMID 36233192, 2022). "Breast cancer cells with high CXCR4 expression can metastasize to specific organs with CXCL12 chemotaxis, resulting in organ-specific metastasis." (PMID 35463082, 2022). "In highly invasive cells, such as MDA-MB-231 breast cancer cells, the binding of CXCL12 to CXCR4 activates multiple downstream signaling pathways, including calcium mobilization." (PMID 36229490, 2022). "While BUB1, KRT5, and MYCN were overexpressed in young women with breast cancer, CXCL12 showed a decreased expression." (PMID 36685821, 2022). "Binding to CXCR4 with the β-hairpin mimicry, balixafortide inhibited the CXCL12-induced activation of downstream MAPK-ERK/PI3K-AKT pathways in the lymphoma and AML cell lines and blocked the CXCL12-dependent chemotaxis in breast cancer and leukemia cell lines." (PMID 36465350, 2022). "The depletion of FAM189A2 in breast cancer cells prohibits the CXCL12‐stimulated endocytosis of CXCR4 and, importantly, enhances the cellular function of CXCR4 for the cell migration and stemness." (PMID 34927784, 2022). "The results showed that CXCL12, ESR1, IGF1, and FOS were significantly associated with the survival of breast cancer." (PMID 35463082, 2022). "In particular, we show that the OHD4–12 binds and activates the CXCL12 receptor CXCR4 and inhibits the CXCL12-driven migration of MDA-MB-231 breast cancer cells." (PMID 36229490, 2022). "This problem can be overridden by combined inhibition of S100A9-CXCL12 signaling with a PD-1 antibody (aPD-1), providing selective strategy for effective immunotherapy in breast cancers with elevated S100A9 and/or CXCL12 protein levels." (PMID 35304461, 2022). "In this respect, inhibition of DPP4 has been reported to accelerate EMT and breast cancer metastasis via CXCL12/CXCR4/mammalian target of rapamycin (mTOR) signaling." (PMID 35053615, 2022). "Using the OHD4–12, we demonstrate that it interrupts the CXCL12-driven migration of breast cancer cells, thus establishing the role of CXCL4–CXCL12 heterodimer in breast cancer and suggesting its utility for therapeutic advantage." (PMID 36229490, 2022).
breast carcinoma (continued). "CXCR4 receptor and its ligand CXCL12 play a crucial role in the metastasis of various cancer types including breast cancer." (PMID 36140541, 2022). "Cancer cells in human pancreatic, colorectal, and breast cancers are coated with the chemokine CXCL12 in the form of covalent heterodimers with keratin-19." (PMID 35046049, 2022). "In breast cancer, CXCL12/CXCR4-dependent cell migration plays an important role in progression, for which AQP3 is crucial through H2O2 transport via channel activity from AQP3." (PMID 35847914, 2022). "The CXCL12/CXCR4/ACKR3 cascade is reported to be involved in almost every aspect of breast cancer tumorigenesis." (PMID 36233192, 2022). "The CXCL12/CXCR4 axis plays a critical role in directing the metastasis of CXCR4+ cancer cells to organs that express high CXCL12 levels in breast cancer." (PMID 35053615, 2022). "It has been found that CXCR4, also known as fusin, is necessary for breast cancer cells migration towards tissues that present a high quantity of its specific ligand—cytokine SDF1 (CXCL12)." (PMID 36230523, 2022). "Overexpression of CXCL12 can promote the growth of human breast cancer cells, exacerbating nasopharyngeal carcinoma cell migration and invasion by binding to its receptor CXCR4." (PMID 35647303, 2022). "In the case of breast cancer (BC), the most frequent sites of metastasis are the lung, brain and bone because they are enriched in CXCL12-expressing fibroblasts." (PMID 36293358, 2022). "On the other hand, TA-MSCs release CCL5 to bind to CCR5 on breast cancer cells, and then, signal-received cancer cells express CXCL12 to drive the migration and recruitment of TAMs and MDSCs." (PMID 36324128, 2022). "We also found that the DPP-4 inhibitor induces breast cancer metastasis via the inhibition of CXCL12 degradation." (PMID 34063285, 2021). "Inhibition of both CXCL12 and ER resulted in decreased proliferation and migration, suggesting that CXCL12 differentially regulates proliferation and migration in breast cancer depending on the expression levels of ER." (PMID 33530455, 2021). "Previous studies have shown that the positive-feedback loop initiated by the C-X-C chemokine receptor type 4 (CXCR4), highly expressed in malignant BCCs, to the CXCL12 expressed in bone lead to breast cancer migration." (PMID 34754042, 2021). "When CXCL12 expression is low, breast cancer cells promote migration via activating RhoA, while high concentrations allow the interaction between RhoA and Rac1, promoting cell–cell and cell–matrix adhesion and thus inhibiting migration." (PMID 33530455, 2021). "Interaction between CXCR4 and its ligand CXCL12 was described to mediate the MDSC trafficking in mouse models of breast cancer and hepatic carcinoma." (PMID 33578808, 2021). "To begin testing for the functional significance of native CXCR4-CCR7 complexes in breast cancer, we assessed the ability of CXCL12, CCL19 or in combination to inhibit the forskolin-induced increase in cAMP production in MMTV-PyMT primary mammary cells." (PMID 34685420, 2021). "As cooperative ligand binding has been reported in chemokine receptor dimers, we assayed the ability of CXCL12 to potentiate CCL19 interaction with its receptor in the panel of breast cancer cell lines with varied invasive properties." (PMID 34685420, 2021). "CXCR4 is known to drive breast cancer metastasis to bone through engagement with its cognate ligand, CXCL12, which is highly expressed on mesenchymal stromal cells in the bone marrow." (PMID 34556788, 2021). "The chemokine CXCL12 has been shown by therapies against aggressive and metastatic breast cancer to regulate the cell growth and metastasis of breast cancer, and to develop the tumor microenvironment." (PMID 34490085, 2021). "Next we stained the breast cancer TMA for CXCL12 and observed similar staining patterns as reported." (PMID 33988305, 2021).
breast carcinoma (continued). "The CXCL12/CXCR4 axis plays an important role in directing CXCR4-overexpressed breast cancer cells’ metastasis to organs that express high levels of CXCL12, including bone marrow." (PMID 34503103, 2021). "High CXCL12 expression was reported to confer a survival advantage for breast cancer patients and stage III CC." (PMID 33833937, 2021). "IL-7-expressing CAFs were identified as another subpopulation that sustains breast cancer stemness via CXCL12 secretion." (PMID 34769066, 2021). "Binding of the chemokine CXCL12 to its receptors CXCR4 and CXCR7 is positively associated with the progression of breast cancer; high expression of both CXCR4/CXCR7 has been implicated in the activation of EMT, tumor stemness, and chemoresistance." (PMID 33805447, 2021). "Along this line, recruitment of MDSCs via CXCL12 is an aggravating factor in breast cancer, influenced by the levels of ER." (PMID 33530455, 2021). "We further showed that as in the murine model also in human breast cancer CXCL12 is predominantly expressed by the tumor cells." (PMID 33988305, 2021). "Retention of CD8 TIL by tenascin‐C/CXCL12 was also observed in human breast cancer by tissue staining." (PMID 33988305, 2021). "The clinical data also showed that high expression levels of CXCL12 and its receptors CXCR4 were associated with easy metastasis and poor prognosis of breast cancer." (PMID 35111484, 2021). "CXCL12: The ability of 17β-estradiol to robustly increase expression of the chemokine CXCL12 in breast cancer cells was reported by the Korach lab and others, and was confirmed in multiple GEO datasets." (PMID 34359625, 2021). "While CXCR4, together with its ligand CXCL12, has been investigated in the mechanisms of breast cancer progression through angiogenesis, EMT, and immunosuppression." (PMID 34611125, 2021). "Another study described similar effects of CAF-secreted CXCL12 on monocytes in triple-negative (TN) breast cancers." (PMID 34635121, 2021). "Colon cancer samples from the TCGA showed high expression of CXCL1, 3, 5, 6, and 11 and low expression of CXCL12 (fold change > 2); the Bittner poly-cancerous dataset confirmed the differential expression of CXCs in colon cancer and breast cancer." (PMID 34439306, 2021). "One study showed that in the MDA-MB-231 breast cancer cell line CXCL12 stimulation leads to an increased localization of AQP3 at the leading edge of the cell." (PMID 34099798, 2021). "The systemic neutralization of IL-17A significantly reduces breast cancer metastasis in mice by reducing expression of CXCL12/SDF-1 in the metastatic niches." (PMID 33922795, 2021). "In the CXCR4-positive Tregs, tumoral CXCL12 enhances recruitment and suppresses the anti-tumor immune response in basal-like breast cancer." (PMID 33937018, 2021). "CAF-derived CXCL12 was also found to enhance migration and invasion capacity of breast cancer cells." (PMID 34769066, 2021). "After reaching the bone, breast cancer cells are retained close to osteoprogenitor cells in the hypoxic niche; the elevated expression of CXCL12 in the latter promotes the growth of breast cancer cells and thereby results in bone metastasis." (PMID 33467722, 2021). "Consistent with our results, the contribution of CXCL12 secretion to breast cancer invasiveness has been reported and corroborated by clinical data." (PMID 33753872, 2021). "A CXCL12/CXCR4 interaction drives breast cancer metastasis, as evidenced by a direct correlation between high CXCR4 levels in primary tumors and high metastatic capacity." (PMID 33530455, 2021). "This receptor is reported to be actively involved in breast cancer bone metastasis by directing the CXCR4-positive cancer cells to organs that express high levels of CXCL12, such as bone marrow." (PMID 34503103, 2021). "In breast cancer, the CXCL12/CXCR4 axis has been extensively investigated in regard to the homing of cancer cells to metastatic sites and promoting metastasis." (PMID 34427969, 2021).